IGKV6D-21 (immunoglobulin kappa variable 6D-21 (non-functional))
Description:
V region of the variable domain of immunoglobulin light chains that participates in the antigen recognition. Immunoglobulins, also known as antibodies, are membrane-bound or secreted glycoproteins produced by B lymphocytes. In the recognition phase of humoral immunity, the membrane-bound immunoglobulins serve as receptors which, upon binding of a specific antigen, trigger the clonal expansion and differentiation of B lymphocytes into immunoglobulins-secreting plasma cells. Secreted immunoglobulins mediate the effector phase of humoral immunity, which results in the elimination of bound antigens. The antigen binding site is formed by the variable domain of one heavy chain, together with that of its associated light chain. Thus, each immunoglobulin has two antigen binding sites with remarkable affinity for a particular antigen. The variable domains are assembled by a process called V-(D)-J rearrangement and can then be subjected to somatic hypermutations which, after exposure to antigen and selection, allow affinity maturation for a particular antigen.
Synonyms: IGKV6D21; A10
Gene: Immunoglobulin variable (V) gene on chromosome 2 (90,021,567 to 90,022,185, forward strand). Ensembl gene ENSG00000225523.
Subcellular location: Secreted; Cell membrane
Gene Ontology:
Biological process: immune response
Cellular component: extracellular region; immunoglobulin complex; plasma membrane
Homologues: Orthologues: mouse Igkv5-48 (68% identical), mouse Igkv5-39 (66% identical), mouse Igkv5-43 (66% identical), mouse Igkv5-45 (66% identical), rat Igkv5-45l1 (66% identical), mouse Igkv5-37 (61% identical). Paralogues in human: IGKV6-21 (97% identical), IGKV6D-41 (76% identical), IGKV1D-12 (65% identical), IGKV1-12 (64% identical), IGKV1-39 (64% identical), IGKV1-9 (64% identical), IGKV1D-13 (64% identical), IGKV1D-39 (64% identical), IGKV1-8 (62% identical), IGKV1-27 (61% identical), IGKV1-6 (61% identical), IGKV3-11 (61% identical), and 81 more.
Diseases named in the same sentence as IGKV6D-21 in open-access papers:
IGKV6D-21 is named in the same sentence as 3 diseases in open-access papers, as found by Europe PMC text mining. Sharing a sentence is not in itself a finding about the gene and the disease.
IGKV6D-21 shares sentences with these, for which no sentence is quoted: head and neck squamous cell carcinoma (1 paper); lymphoma (1); thymoma (1).